FBN1 (fibrillin 1)
Description:
[Fibrillin-1]: Structural component of the 10-12 nm diameter microfibrils of the extracellular matrix, which conveys both structural and regulatory properties to load-bearing connective tissues. Fibrillin-1-containing microfibrils provide long-term force bearing structural support. In tissues such as the lung, blood vessels and skin, microfibrils form the periphery of the elastic fiber, acting as a scaffold for the deposition of elastin. In addition, microfibrils can occur as elastin-independent networks in tissues such as the ciliary zonule, tendon, cornea and glomerulus where they provide tensile strength and have anchoring roles. Fibrillin-1 also plays a key role in tissue homeostasis through specific interactions with growth factors, such as the bone morphogenetic proteins (BMPs), growth and differentiation factors (GDFs) and latent transforming growth factor-beta-binding proteins (LTBPs), cell-surface integrins and other extracellular matrix protein and proteoglycan components. Regulates osteoblast maturation by controlling TGF-beta bioavailability and calibrating TGF-beta and BMP levels, respectively (By similarity). Negatively regulates osteoclastogenesis by binding and sequestering an osteoclast differentiation and activation factor TNFSF11. This leads to disruption of TNFSF11-induced Ca(2+) signaling and impairment of TNFSF11-mediated nuclear translocation and activation of transcription factor NFATC1 which regulates genes important for osteoclast differentiation and function. Mediates cell adhesion via its binding to cell surface receptors integrins ITGAV:ITGB3 and ITGA5:ITGB1. Binds heparin and this interaction has an important role in the assembly of microfibrils. [Asprosin]: Adipokine secreted by white adipose tissue that plays an important regulatory role in the glucose metabolism of liver, muscle and pancreas. Hormone that targets the liver in response to fasting to increase plasma glucose levels. Binds the olfactory receptor OR4M1 at the surface of hepatocytes and promotes hepatocyte glucose release by activating the protein kinase A activity in the liver, resulting in rapid glucose release into the circulation. May act as a regulator of adaptive thermogenesis by inhibiting browning and energy consumption, while increasing lipid deposition in white adipose tissue (By similarity). Also acts as an orexigenic hormone that increases appetite: crosses the blood brain barrier and exerts effects on the hypothalamus (By similarity). In the arcuate nucleus of the hypothalamus, asprosin directly activates orexigenic AgRP neurons and indirectly inhibits anorexigenic POMC neurons, resulting in appetite stimulation (By similarity). Activates orexigenic AgRP neurons via binding to the olfactory receptor OR4M1 (By similarity). May also play a role in sperm motility in testis via interaction with OR4M1 receptor (By similarity).
Synonyms: FBN; MASS; OCTD; SGS; ACMICD; ECTOL1; GPHYSD2; MFLS; MFS1; SSKS; WMS; WMS2
Tractability: Antibody: UniProt places it where antibodies can reach, with high confidence; its Gene Ontology location is reachable by antibodies, with high confidence; UniProt predicts a signal peptide or a membrane-spanning region. PROTAC: ubiquitination databases record sites on it.
Gene: Protein-coding gene on chromosome 15 (48,408,313 to 48,645,721, reverse strand). Ensembl gene ENSG00000166147.
Subcellular location: Secreted; Secreted, extracellular space, extracellular matrix (Fibrillin-1); Secreted (Asprosin)
Subcellular location (Human Protein Atlas): Golgi apparatus; Plasma membrane; Predicted to be secreted
Pathways (Reactome):
Extracellular matrix organization: Degradation of the extracellular matrix; Elastic fibre formation; Integrin cell surface interactions; Molecules associated with elastic fibres
Metabolism of proteins: Post-translational protein phosphorylation; Regulation of Insulin-like Growth Factor (IGF) transport and uptake by Insulin-like Growth Factor Binding Proteins (IGFBPs)
Signal Transduction: TGF-beta receptor signaling activates SMADs
Gene Ontology:
Molecular function: calcium ion binding; extracellular matrix structural constituent; heparin binding; identical protein binding; integrin binding; protein binding; protein-containing complex binding; extracellular matrix constituent conferring elasticity; hormone activity
Biological process: camera-type eye development; cell adhesion mediated by integrin; embryonic eye morphogenesis; heart development; negative regulation of osteoclast development; negative regulation of osteoclast differentiation; post-embryonic eye morphogenesis; skeletal system development; collagen fibril organization; gene expression; glucose homeostasis; glucose metabolic process; negative regulation of BMP signaling pathway; negative regulation of transforming growth factor beta receptor signaling pathway; angiogenesis; cellular response to insulin-like growth factor stimulus; cellular response to transforming growth factor beta stimulus; elastic fiber assembly; endothelial cell differentiation; immune response; inflammatory response; intracellular protein localization; kidney development; lung alveolus development; lung development; and 13 more
Cellular component: basement membrane; extracellular matrix; extracellular region; microfibril; endoplasmic reticulum lumen; non-collagenous component of interstitial matrix
Genetic constraint (gnomAD): Loss-of-function variants: 27 observed, 353.01 expected, observed/expected ratio (o/e) 0.0765, 90% interval 0.055 to 0.1. The upper end of that interval is the gene's LOEUF score, 0.1, which puts it in group 1 of 6, group 1 being the genes least tolerant of losing a copy. Missense variants: 2,396 observed, 3,775.5 expected, observed/expected ratio (o/e) 0.63, 90% interval 0.61 to 0.66. Synonymous variants: 1,183 observed, 1,308.2 expected, observed/expected ratio (o/e) 0.9, 90% interval 0.86 to 0.95.
Gene-disease validity (ClinGen):
ClinGen rates the evidence that FBN1 causes each of these diseases.
familial thoracic aortic aneurysm and aortic dissection (autosomal dominant): Definitive. A rare genetic vascular disease characterized by the familial occurrence of thoracic aortic aneurysm, dissection or dilatation affecting one or more aortic segments (aortic root, ascending aorta, arch or descending aorta) in the absence of any other associated disease.
Marfan syndrome (autosomal dominant): Definitive. A disorder of the connective tissue.
Shprintzen-Goldberg syndrome (autosomal dominant): Disputed. Shprintzen-Goldberg syndrome (SGS) is a very rare genetic disorder characterized by craniosynostosis, craniofacial and skeletal abnormalities, marfanoid habitus, cardiac anomalies, neurological abnormalities, and intellectual disability.
Homologues: Orthologues: chimpanzee FBN1 (99% identical), macaque FBN1 (99% identical), pig FBN1 (98% identical), dog FBN1 (97% identical), rabbit FBN1 (97% identical), rat Fbn1 (96% identical), mouse Fbn1 (96% identical), guinea pig FBN1 (96% identical), tropical clawed frog fbn1 (81% identical). Paralogues in human: FBN2 (69% identical), FBN3 (59% identical).
Diseases named in the same sentence as FBN1 in open-access papers:
FBN1 is named in the same sentence as 341 diseases in open-access papers, as found by Europe PMC text mining. Sharing a sentence is not in itself a finding about the gene and the disease. The quoted sentences say what the papers report.
Marfan syndrome (709 papers, 2005 to 2026). "Marfan syndrome is an autosomal dominant connective tissue disorder caused by pathogenic variants in the fibrillin-1-encoding gene." (PMID 42129962, 2026). "Enhanced TGFβ signaling caused by mutations in Fibrillin-1 (FBN1) in patients with Marfan syndrome (MFS) leads to myxomatous degeneration of the mitral valve (MDMV)." (PMID 42274425, 2026). "Marfan syndrome (MFS) is an autosomal dominant disorder of the connective tissue caused by pathogenic variants in the FBN1 gene, characterized by cardiovascular, ocular, and skeletal involvement." (PMID 42117003, 2026). "Marfan syndrome (MFS) is a genetic disorder caused by mutations in the fibrillin-1 (Fbn1) gene, leading to structurally abnormal elastic fibers and diverse clinical manifestations." (PMID 41596139, 2026). "Marfan syndrome (MFS) is an autosomal dominant connective tissue disorder caused by mutations in the FBN1 gene, which carries a high risk of cardiovascular morbidity and mortality." (PMID 41970087, 2026). "Marfan syndrome (MS) is a genetic disorder typically caused by harmful mutations in the fibrillin-1 (FBN1) gene, leading to gradual enlargement of the aortic root." (PMID 41009387, 2025). "Marfan syndrome is an autosomal dominant connective tissue disorder caused by mutations in the FBN1 gene." (PMID 40497208, 2025). "Marfan Syndrome is an autosomal dominant disorder caused by a mutation in the FBN1 (fibrillin-1) gene on chromosome 15, which encodes the fibrillin protein." (PMID 41516965, 2025). "Marfan syndrome is a connective tissue disorder caused by FBN1 mutations, leading to aortic wall fragility and increased susceptibility to aneurysm and dissection." (PMID 40695874, 2025). "Marfan syndrome (MFS) is an autosomal dominant connective tissue disorder characterized by mutations in the FBN1 gene encoding fibrillin-1." (PMID 39857055, 2025). "Deficiencies or defects in FBN1, as seen in Marfan syndrome, disrupt TGFβ activity and consequently affect OC differentiation and function." (PMID 40137915, 2025). "Connective tissue disorders, such as Marfan syndrome resulting from mutations in the ECM protein fibrillin 1, have demonstrated a direct impact on the heart under conditions of cardiac pressure overload." (PMID 40274989, 2025). "Marfan syndrome is caused by a defect in connective tissue mainly caused by genetic mutations affecting the Fibrillin-1 (FBN-1) gene, encoding fibrillin-1, an indispensable constituent of the extracellular matrix." (PMID 40662044, 2025). "An association of mitral valve prolapse with Marfan syndrome resulting from pathogenic FBN1 variants supports the use of hypomorphic fibrillin-1 mgR mice to investigate mechanisms and therapy for mitral valve disease." (PMID 40392604, 2025). "Marfan syndrome is an autosomal dominant disorder caused by pathogenic variants in FBN1 (fibrillin-1) and primarily affects the cardiovascular, ocular, and musculoskeletal systems." (PMID 41465473, 2025). "We then analyzed the intra-group similarity scores of 9 individuals carrying rare LoF variants in FBN1, five of whom were diagnosed with Marfan syndrome." (PMID 41411243, 2025). "Marfan syndrome is an autosomal dominant connective tissue disorder resulting from mutations in the FBN1 gene encoding fibrillin-1." (PMID 40075889, 2025). "One individual was heterozygous for the TGFBR2 p.Pro129fs (LP) variant associated with Loeys–Dietz syndrome, while a LP variant related to Marfan Syndrome (FBN1 p.Arg165Gln) was detected in another individual." (PMID 40970488, 2025). "Marfan syndrome is a genetic disorder caused by a mutation in the FBN1 gene, which affects connective tissue throughout the body." (PMID 40291238, 2025). "Clinical studies have revealed that individuals with reduced FBN1 expression are at higher risk for specific manifestations of Marfan syndrome, including ocular, skeletal, and cardiovascular complications." (PMID 40129967, 2025).
Marfan syndrome (continued). "Marfan syndrome is characterized by decreased aortic distensibility, increased stiffness index, and increased pulse wave velocity due to fibrillin-1 deficiency and abnormal elastin synthesis." (PMID 40559232, 2025). "Marfan syndrome is a hereditary connective tissue disorder that is caused by pathogenic variants in the FBN1 gene and is traditionally known to have cardiovascular and ocular presentations." (PMID 41541920, 2025). "Next, we examined the significantly associated phenotypes of Marfan syndrome and FBN1 rare LoF variant carriers to better understand the phenotypic contributors to Marfan syndrome." (PMID 41411243, 2025). "Although the skeletal phenotypes of GD and Marfan syndrome differ, both share underlying mechanisms involving dysregulation of FBN1 and TGF-β signaling." (PMID 40740820, 2025). "For example, Marfan syndrome is associated with the mutation of the FBN1 gene that codes for fibrillin-1, a protein in the extracellular matrix." (PMID 41541977, 2025). "FBN1 mutations cause Marfan syndrome, a genetic disorder characterized by TAD, skeletal, and ocular abnormalities." (PMID 40658722, 2025). "Marfan Syndrome (MFS) is an autosomal dominant genetic disorder that affects connective tissue throughout the body due to mutations in the fibrillin-1 (FBN1)gene." (PMID 40896254, 2025). "Marfan syndrome (MFS) is a connective tissue disorder caused by mutations in the gene that encodes fibrillin-1, a glycoprotein necessary for elastic fiber assembly and stability in the large elastic arteries." (PMID 40414262, 2025). "The ocular symptoms, such as dislocation of the lens and myopia, are additional examples of the widespread effect of fibrillin-1 deficiency and the support of the systemic activity of connective tissues in Marfan syndrome." (PMID 41541920, 2025). "Marfan syndrome (MFS) is a systemic heritable connective tissue disorder caused by pathogenic variants in the FBN1 gene." (PMID 40672385, 2025). "Pathogenic variants in FBN1 are primarily linked to Marfan syndrome (MFS) and a broad spectrum of other autosomal dominant disorders, including MASS syndrome, ectopia lentis (EL), stiff skin syndrome, Weill–Marchesani syndrome, and acromicric dysplasia." (PMID 41256009, 2025). "For example, mutations in FBN1 associated with Marfan syndrome can vary from truncating mutations that completely disrupt fibrillin-1 synthesis to missense mutations that alter protein structure without completely abolishing its function." (PMID 40110250, 2025). "While FBN1 mutations are the main cause, other genes have been implicated in Marfan syndrome and Marfan-like conditions, including TGFBR1 and TGFBR2." (PMID 41411243, 2025). "Considering FBN1, the predominant isoform of fibrillin in adult organisms, deficiencies occur in Marfan syndrome and lead to the incomplete assembly of elastic fibers." (PMID 40277901, 2025). "Based on our findings, we advocate for the inclusion of FBN1 genetic testing in the diagnostic workup of children presenting with features indicative of Marfan syndrome." (PMID 40672385, 2025). "In conclusion, we identified a novel nonsense mutation, c.4991dupA (p.Tyr1664X), in exon 40 of the FBN1 gene in a Chinese family with Marfan syndrome." (PMID 40336639, 2025). "Marfan syndrome caused by haploinsufficiency is likely associated with expression levels from the normal FBN1 allele." (PMID 40129967, 2025). "We first examined the intra-group similarity among Marfan syndrome patients and rare LoF variant carriers of FBN1." (PMID 41411243, 2025). "Each of these disorders has well-established major causative genes: PKD1 and PKD2 for ADPKD, FBN1 for Marfan syndrome, and NF1 for NF1 disease." (PMID 41411243, 2025). "Mutations in fibrillin 1 in Marfan syndrome weaken the vascular wall while disrupting the regulation of TGF-B1 bioavailability." (PMID 40176978, 2025).
Marfan syndrome (continued). "included a fetus with a paternally inherited variant in the FBN1 gene and reported that the father had typical features of Marfan syndrome." (PMID 39960876, 2025). "FBN1 mutations are genetic tests that can play an essential role in the diagnosis of Marfan syndrome, especially in patients with either overlapping or atypical phenotypes." (PMID 41541920, 2025). "In this study, we identified a novel nonsense mutation (c.4991dupA; p.Tyr1664X) in exon 40 of the FBN1 gene in a Chinese family with Marfan syndrome." (PMID 40336639, 2025). "The FBN1 gene is the main causative agent of Marfan syndrome, and its mutations cause quantitative or qualitative deficiencies in fibrillin-1." (PMID 41541920, 2025). "Mutations in FBN1 result in haploinsufficiency, leading to Marfan syndrome, in which the expression of functional FBN1 is correlated with disease onset and severity." (PMID 40129967, 2025). "Marfan syndrome is characterized by mutations in the fibrillin-1 gene, which causes abnormal elastic properties in the aorta which leads to decreased compliance and progressively increased dilation." (PMID 40291238, 2025). "Marfan syndrome (MFS) is a genetic disorder caused by an FBN1 variant and is diagnosed based on the revised Ghent criteria, which incorporate clinical manifestations and genetic testing." (PMID 40169830, 2025). "Conversely, Marfan syndrome is characterized by a mutation in the fibrillin-1 protein, which is a primary component of microfibrils found in connective tissue." (PMID 40474214, 2025). "We next applied PERADIGM to Marfan syndrome, an autosomal dominant connective tissue disorder primarily caused by mutations in FBN1." (PMID 41411243, 2025). "For instance, individuals with mutations in the fibrillin-1 (FBN1) gene—commonly associated with Marfan syndrome—are at an elevated risk for aortic dissection." (PMID 40430141, 2025). "Among the hereditary causes, Marfan syndrome is the most prevalent, characterized as a connective tissue disorder driven by FBN1 mutations that lead to life-threatening thoracic aortic ruptures." (PMID 40277943, 2025). "Some Marfan syndrome–associated SNPs occurring in the EGFD-encoding genomic region of FBN1 cause ectopia lentis, including those that alter the number of cysteine residues in EGFDs." (PMID 41354343, 2025). "For over two decades, research has shown that some patients who meet the Ghent criteria for Marfan syndrome but lack FBN1 pathogenic variants instead carry genetic variants in TGFβR1 or TGFβR2." (PMID 40243722, 2025). "Marfan syndrome (MFS) is a hereditary systemic disorder of the connective tissue caused by mutations in the gene encoding for the large glycoprotein fibrillin 1 (FBN1) that affects the cardiovascular, pulmonary, musculoskeletal, and ocular systems." (PMID 40896254, 2025). "Marfan syndrome (MFS) is a connective tissue disorder caused by variants in fibrillin‐1 (FBN1) characterized by ocular and skeletal manifestations and aortic root (AoR) dilation with a high risk of dissections before the age of 40 if left untreated." (PMID 40065510, 2025). "Among the keywords used were osteoporosis, bone density, fracture risk, Marfan syndrome, FBN1 mutation, and connective tissue disorder, preparing and combining them in varying formulations." (PMID 41541920, 2025). "The most prominent of these is Marfan syndrome that arises in association with mutations in the gene encoding fibrillin-1 (FBN1), a secreted extracellular matrix protein." (PMID 40519164, 2025). "Mutations in fibrillin-1 gene (FBN1) have been shown to be associated with Marfan syndrome and most FBN1 mutations display missense or nonsense." (PMID 39877462, 2025). "Since Marfan syndrome can be misdiagnosed for other connective tissue disorders caused by pathogenic variants in genes other than FBN1, studies published before the revised Ghent criteria were excluded." (PMID 39073692, 2024).